MIR30A (microRNA 30a)
Synonyms: hsa-mir-30a; MIRN30A; mir-30a
Gene: MicroRNA gene on chromosome 6 (71,403,551 to 71,403,621, reverse strand). Ensembl gene ENSG00000207827.
Gene Ontology:
Biological process: miRNA-mediated post-transcriptional gene silencing
Cellular component: RISC complex
Homologues: Orthologues: chimpanzee ptr-mir-30a (100% identical), macaque mml-mir-30a (99% identical), mouse Mir30a (99% identical), rat Mir30a (97% identical), tropical clawed frog xtr-mir-30a (92% identical), guinea pig MIR30A (90% identical), pig ssc-mir-30a (90% identical). Paralogues in human: MIR30E (79% identical), MIR30D (72% identical), MIR30B (39% identical), MIR30C1 (35% identical), MIR30C2 (35% identical).
Diseases named in the same sentence as MIR30A in open-access papers:
MIR30A is named in the same sentence as 7 diseases in open-access papers, as found by Europe PMC text mining. Sharing a sentence is not in itself a finding about the gene and the disease. The quoted sentences say what the papers report.
breast carcinoma (1 paper, 2024). "Furthermore, in lung and breast cancer, the interaction between MIR30A and BECN1 has been described as another connection between cancer and autophagy." (PMID 37589496, 2024).
gastrointestinal stromal tumor (1 paper, 2024). "MIR30A has also been associated with drug sensitivity in gastrointestinal stromal tumors." (PMID 37589496, 2024).
prostate carcinoma (1 paper, 2022). A carcinoma that arises from epithelial cells of the prostate gland. "It seems that the expression level of miRNAs with anti-tumor activity decreases in hypoxic conditions; in these conditions, MIR30A and MIR205 undergo downregulation to promote prostate cancer progression." (PMID 35317831, 2022). "However, enhancing levels of MIR30A and MIR205 downregulate the level of TP53INP1 via binding to its 3′-UTR to suppress autophagy, resulting in an increased radio-sensitivity of prostate cancer cells." (PMID 35317831, 2022).
tumor (1 paper, 2022). "KEGG enrichment showed that in PNT1A cells, Menin significantly (p = 4.8E–08) regulates 12 microRNAs (MIR1-2; MIR133a-1; MIR155; MIR15a; MIR16-1; MIR29a; MIR29b-1; MIR30a; MIR30d; let-7a-1; let-7d; let-7f-1), widely shown to function as tumor suppressors in PC." (PMID 34711954, 2022).
MIR30A also shares sentences with these, for which no sentence is quoted: cancer (1 paper); chronic myelogenous leukemia (1); non-small cell lung carcinoma (1).